INS (insulin)
Diseases named in the same sentence as INS in open-access papers (continued):
Sharing a sentence is not in itself a finding about the gene and the disease.
diabetes (continued). "Illness perceptions enhance the uptake of oral or insulin therapy when patients gain sufficient diabetes knowledge and adopt self-care practices for T2DM." (PMID 36648847, 2023). "The shortest period lived with diabetes managed on insulin therapy was two years and the longest was twenty years." (PMID 37828591, 2023). "The patients were compensated on oral antidiabetic treatment and/or insulin, and a substantial proportion had micro- and macrovascular complications of diabetes." (PMID 37445792, 2023). "Apelin is crucial for controlling insulin secretion and plays a role in the pathogenesis of diabetes complications." (PMID 37706122, 2023). "Relief measures such as insulin, hypoglycemic drugs and strips should be given to people with diabetes." (PMID 36589631, 2023). "On the other hand, a significant increase in the AA level in the circulatory system of diabetes patients inhibits insulin secretion, promoting the occurrence and development of DM." (PMID 37746665, 2023). "It is possible that the loss of ICC, without observed loss of nerve fibers, is due to impaired intracellular SCF signaling and the sensitivity of ICC to reduced insulin levels in this diabetes model." (PMID 36837509, 2023). "Diabetes mellitus (DM) is a metabolic disorder characterized by increased blood glucose levels (hyperglycemia) resulting from defects in insulin secretion and insulin action." (PMID 37370930, 2023). "Pancreatic β-cells, by secreting insulin, play a key role in the control of glucose homeostasis, and their dysfunction is the basis of diabetes development." (PMID 36830593, 2023). "The incidence of diabetes is gradually increasing worldwide, necessitating the development of novel therapies to either compensate for decreased insulin levels or replace dysfunctional β-cells in situ." (PMID 37689751, 2023). "Despite the prevalence and widespread use of anti-diabetic medications like metformin, sulfonylureas, thiazolidinediones, and insulin, diabetes ranks as a major global health concern." (PMID 38053673, 2023). "Diabetes mellitus is a multifaceted and complex metabolic condition that ultimately results from abnormalities in insulin secretion, action, or both." (PMID 38066741, 2023). "Current differentiation protocols to generate stem cell-derived β (SC-β) cells yield a cell product able to secrete insulin in response to increasing concentrations of glucose and reverse diabetes upon transplantation in mice." (PMID 37929027, 2023). "Participants expressed the following ideas about insulin treatment: it is necessary to live if oral medications fail, it cures diabetes, it regulates sugar." (PMID 37377235, 2023). "Following the use of high-dose corticosteroids, most of the patients required insulin due to their known or hidden diabetes." (PMID 36673839, 2023). "Another important aspect of diabetes management is physical activity, which helps the body use insulin more efficiently." (PMID 38028163, 2023). "Regarding the diabetic groups, patients with advanced NPDR/PDR presented differences in the duration of diabetes and insulin and metformin intake in comparison to the advanced DR groups." (PMID 37883447, 2023). "The capacity of HDL to promote cholesterol efflux can be affected by oxidation, lipolysis, and proteolysis, and is enhanced as a compensatory mechanism in response to diabetes-induced oxidative stress and insulin in the fetal circulation." (PMID 37107203, 2023). "Over the past three decades, clinical trials have demonstrated that restoring beta-cell function through islet or pancreas transplantation can lead to more physiologic regulation of blood sugar levels compared to exogenous insulin in diabetes patients." (PMID 38077372, 2023). "All but two studies measured diabetes-related health outcomes including fasting blood glucose, fasting insulin, insulin resistance, and/or others." (PMID 37709770, 2023).
diabetes (continued). "The diabetes severity score parameters included the number of oral hypoglycemic agents (≥ 3), insulin use, diabetes duration (≥ 5 years), and the presence of chronic kidney disease (CKD) or cardiovascular disease." (PMID 37041513, 2023). "PYY and GLP‐1 can regulate intestinal cells to control gastric emptying and food intake, and stimulate insulin secretion to reduce blood glucose, which plays an important role in the prevention and treatment of obesity and diabetes." (PMID 37181324, 2023). "Basalinsuline der ersten Generation (NPH-Insulin) sollten aufgrund der erhöhten Hypoglykämiegefahr bei Menschen mit Diabetes mellitus Typ 1 nicht mehr angewendet werden." (PMID 37101052, 2023). "The participants diagnosed with insulin-independent diabetes presenting modest MD compliance showed greater physical activity levels compared to participants presenting low MD adherence." (PMID 38201865, 2023). "It has been demonstrated that FGF1 partially ameliorates diabetes-induced beta cell dysfunction by improving insulin secretion at the pancreatic islet level." (PMID 37284218, 2023). "Adjusting for age, baseline HbA1c, sex, the duration of diabetes, and baseline premixed insulin dose, patients in the LCCP group had 0.492% (P=.002) more HbA1c reduction relative to baseline than the non-LCCP group." (PMID 37097724, 2023). "German patients were most likely to be using insulin multiple times per day, and French patients, who had the lowest BMI value, were least likely to report the use of diet and exercise to control their diabetes." (PMID 38032701, 2023). "The management of this type of diabetes is currently based on insulin therapy using a multi-injection regimen or continuous subcutaneous insulin infusion via an external insulin pump." (PMID 37185052, 2023). "The roles of peroxisome proliferator-activated receptor-α (PPAR-α) in mediating diabetes-related molecular events and increasing insulin secretion via regulating fat and β-oxidation of adipocytes in islet β cells have been explored." (PMID 37396948, 2023). "Insulin amyloidosis reduces the stability and activity of pharmaceutical compositions of insulin preparations and its analogues, aggravates the course of diabetes mellitus, increases the cost of the treatment procedure and makes it less accessible." (PMID 36835194, 2023). "T1D accounts for about 5–10% of all cases of diabetes and is due to the autoimmune destruction of beta cells of the pancreas, leading to a total incapacity of producing insulin." (PMID 36675484, 2023). "Pancreatic β cell secretion of insulin is crucial to the maintenance of glucose homeostasis and prevention of diseases related to glucose regulation, including diabetes." (PMID 37305687, 2023). "There are various treatment options available for diabetes such as insulin injections or insulin pumps in conjunction with continuous glucose monitoring technology for type 1 diabetes and oral hypoglycemic drugs for type 2 diabetes." (PMID 37266052, 2023). "Another study that was conducted suggested that children with diabetes had impaired ultimate height during the period before intense insulin therapy." (PMID 37859903, 2023). "Measurement of the C-peptide has shown utility in understanding the clinical progression of diabetes and measuring endogenous insulin production in patients with exogenous insulin treatment." (PMID 36830626, 2023). "For example, augmentation of antioxidant defense in animal models of diabetes, achieved by enhancing antioxidant enzyme activity or by dietary supplementation was shown to improve markers of insulin sensitivity." (PMID 37237860, 2023). "The heterogeneity of diabetes was recognized several decades ago, when diabetic patients were divided into insulin-sensitive and insulin-insensitive subgroups based on the oral glucose tolerance test (OGTT)." (PMID 38550950, 2023).
diabetes (continued). "Type 1 IDDM (Insulin-Dependent Diabetes Mellitus), also known as Type 1 diabetes, occurs when the body is unable to produce sufficient insulin, leading to a dependence on insulin injections for patients with this condition." (PMID 37958014, 2023). "In the present study, 87.0% of patients were tested for β cell antibodies and fasting insulin/C-peptide levels when the patients were diagnosed with diabetes mellitus." (PMID 37554766, 2023). "At present, the therapeutic options available for pediatric patients with diabetes are somewhat limited, only insulin, metformin, daily liraglutide and once-weekly exenatide extended release are applied in clinical practice." (PMID 38089044, 2023). "The mean HbA1c level at baseline was 7.64% (SD 1.79%) and the median was 7.10%, indicating that many had optimal HbA1c levels at baseline with 28% (59/211) of the participants using insulin to manage their diabetes." (PMID 36962700, 2023). "The greatest change in the treatment of people living with type 1 diabetes in the last decade has been the explosion of technology assisting in all aspects of diabetes therapy, from glucose monitoring to insulin delivery and decision making." (PMID 37794113, 2023). "Dysfunction of these endocrine cells can lead to severe pathophysiology, especially in the case of β-cells failing to produce insulin, resulting in diabetes mellitus." (PMID 37689751, 2023). "Advanced diabetes technologies, such as insulin pumps, continuous glucose monitors (CGMs), and closed loop systems, have been found to improve self-management and quality of life among young people with diabetes." (PMID 36696176, 2023). "Serum concentrations of biomarkers of diabetes (insulin, IGF-I) and lipid metabolism (total cholesterol, HDL-cholesterol, and triglycerides) assessed at T1 were not significantly affected by the intervention." (PMID 36631905, 2023). "Disrupted insulin signaling in diabetes affecting the GSK-3β pathway can lead to excessive tau phosphorylation, increasing the risk of Alzheimer’s." (PMID 38002034, 2023). "In low- and middle-income countries, there is a concern regarding the availability of insulin and the price of insulin, with syringes and other diabetes goods adding to the burden of treatment." (PMID 36969638, 2023). "The treatment of diabetes-induced rats with β -Caryophyllene restored the altered levels ofblood glucose, serum insulin as well as the lipid parameters, oxidative stress markers, antioxidant enzymes." (PMID 37822828, 2023). "Leonard Thompson became the first T1D patient to receive insulin, marking the beginning of a century of innovations in diabetes treatment." (PMID 38077372, 2023). "The BG tests in both fasting and postprandial periods help to identify the hypersecretion of insulin during the early stage of diabetes." (PMID 37587407, 2023). "Oxidative stress in OSA affects the development of metabolic disorders such as diabetes, dyslipidemia, insulin, and leptin resistance." (PMID 37241105, 2023). "In this multicentric, randomized trial, the AID system consisted of a pump (t:slim X2 insulin pump with Control-IQ Technology, Tandem Diabetes Care) and a continuous glucose monitoring (Dexcom G6, Dexcom)." (PMID 37685946, 2023). "For example, L-Methionine (L-Met) regulates FoxO1 by altering the bivalent domain histone methylation marks H3K27me3 and H3K4me3 to increase FoxO1-mediated upregulation of the insulin transcription factor MafA and mitigate type 1 diabetes mellitus in rats." (PMID 37941908, 2023). "Both these types of surgery present risk of lifelong post-operative sequelae, the most important of which is diabetes from insufficient insulin production." (PMID 37894286, 2023). "The use of insulin with ≥2 other diabetes therapies increased substantially between 2013 and 2019 in both sexes." (PMID 37874829, 2023).
diabetes (continued). "This study sheds new light on the regulatory mechanisms of intracellular insulin granule mobilization and has important implications for understanding the pathogenesis of diabetes." (PMID 38124716, 2023). "Around 25% of the diabetes population covered by Medicare reported a reduction in the use of insulin owing to the rising cost." (PMID 36751859, 2023). "Natural herbal remedies show promise in combating insulin resistance, with anthraquinone extracts garnering attention for their role in enhancing insulin sensitivity and treating diabetes." (PMID 38053837, 2023). "It is evident from this study that the patients using insulin had higher knowledge of diabetes compared to those who used only oral hypoglycaemic agents." (PMID 36464636, 2023). "cncCOE in Drosophila among others suppresses insulin signaling and consequently triggers diabetes-like phenotypes." (PMID 37998385, 2023). "This limitation is a result of challenges in resource availability and the difficulty in recruiting a larger cohort of participants with insulin-treated diabetes." (PMID 38077677, 2023). "The TNXB gene was additionally linked, through PheWAS, with the use of insulin 1 year after the diagnosis of diabetes and the general use of insulin, further implicating TNXB in the pathology of diabetes and diabetic neuropathy, as previously shown." (PMID 37189830, 2023). "The benefits of some alkaloids in the control of IR and diabetes have been attributed to the modulation of insulin signaling pathways, an improvement in the function of pancreatic β-cells and a reduction in oxidative stress and inflammation." (PMID 37513825, 2023). "Prior to onset of type 2 diabetes mellitus, skeletal muscle appears to be more sensitive to insulin than the liver and adipose tissue." (PMID 37990681, 2023). "Mean diabetes duration was 13.5 (8.1) years, 69.5% were male, 51.6% were treated with insulin, 27.3% had a previous history of DFU, and 8.9% had a previous amputation." (PMID 36849888, 2023). "The use of conventional insulin pump therapy and continuous glucose monitoring improves glycemic outcomes and diabetes-related psychosocial outcomes compared with traditional multiple daily insulin injections and capillary glucose monitoring." (PMID 36734145, 2023). "In that study educational level was shown to be an independent determinant of total knowledge of diabetes and for insulin use knowledge." (PMID 37719056, 2023). "Einzelstudien und Meta-Analysen konnten zeigen, dass die Kombination von Insulin mit oralen Antidiabetika bei Menschen mit Typ 2 Diabetes zu einer bis zu 40 %igen Einsparung des Insulinbedarfs gegenüber der alleinigen Insulintherapie führt." (PMID 37101024, 2023). "The subsequent fall in TAR and rise in TIR during in-person school hours by nearly 20 percentage points was a strong pattern that persisted when adjusting for age, duration of diabetes, hemoglobin A1c, and insulin pump use." (PMID 37929231, 2023). "With the increased clinical use of insulin and antibiotics in treatment, the mortality rate of diabetes complicated with infection has reduced; nevertheless, the risk of diabetic patients dying from bacterial-related infections remains high." (PMID 38003764, 2023). "The ORIGIN study showed that the progression of diabetes was substantially reduced with timely insulin treatment in comparison with standard of care." (PMID 36722454, 2023). "Abnormal insulin levels, as well as ineffective insulin signaling observed in diabetes mellitus, limit the ability of the liver to maintain metabolic homeostasis resulting in hyperglycemia and dyslipidemia." (PMID 37110174, 2023). "In particular, islet immunoisolation in animal models of diabetes is an active area of research, with a focus on encapsulating single insulin-producing β cells or entire islets using natural or synthetic biomaterials." (PMID 37965322, 2023).
diabetes (continued). "On TEM investigation of lens opacity induced by diabetes, insulin returned results that require a more in-depth discussion, as it increased the opacity in eye lenses, similarly to vehicle administration." (PMID 37623898, 2023). "Diabetes mellitus, one of the most common endocrine disorders, affects the body’s ability to produce or utilize insulin." (PMID 36932309, 2023). "Hypoglycemia is an uncommon clinical situation except in individuals who use drugs that lower plasma glucose levels, particularly insulin or insulin secretagogues, to treat diabetes mellitus." (PMID 37308982, 2023). "In conclusion, we identified novel markers for predicting impaired insulin sensitivity in human muscle and found four markers that predict individual exercise intervention responses in participants with diabetes." (PMID 36790478, 2023). "First, C-peptide reflects the endogenous insulin secretion of diabetes patients and is related to the improvement of blood glucose control and the reduction of blood glucose variability, which is conducive to reducing DR risk." (PMID 36922809, 2023). "In the treatment of diabetes, 15% of the patients relied on multiple daily doses of insulin, while 36% used oral glycemic drugs; the remaining individuals utilized a combination of both approaches." (PMID 37892825, 2023). "Clinical phenotyping is challenging and an atypical presentation at the time of referral has contributed to monogenic diabetes being unrecognised, with people being clinically diagnosed as having type 1 diabetes and treated with insulin." (PMID 37798422, 2023). "The diabetic patients who use insulin exhibited significant diversity regarding their age, gender, level of education, employment status, duration of diabetes, duration of insulin use, and formal training from healthcare workers." (PMID 38099003, 2023). "The onset of diabetes can result from either the insufficient secretion of insulin by the islet β cells or impaired cellular responsiveness to insulin." (PMID 37376294, 2023). "This diminishment likely contributes to a heightened postprandial glycemic variability, given the concurrent impairment of the initial phase of insulin secretion in diabetes." (PMID 38136081, 2023). "Women with PGDM should replace oral medication with insulin, while type 1 diabetes mellitus (T1DM) requires initiation of insulin suitable for pregnancy or implementation of an insulin pump." (PMID 36327019, 2023). "Consuming adequate protein is pivotal for diabetics, as it can stabilize postprandial blood glucose levels and refine insulin responses, ensuring more effective glucose regulation." (PMID 37836506, 2023). "Current practice guidelines recommend scheduled insulin therapy for most hospitalized patients with diabetes or hyperglycemia." (PMID 36719713, 2023). "Treatment for diabetes typically includes monitoring blood sugar levels, making healthy lifestyle choices, and taking medications or insulin as needed." (PMID 37784049, 2023). "GPR119 has already been pharmacologically targeted for obesity and diabetes because it stimulates insulin secretion by directly acting on pancreatic beta cells or through incretin secretion by gut enteroendocrine cells." (PMID 36462626, 2023). "Our findings regarding insulin use and diabetes contribute to the ongoing debates surrounding insulin’s multifaceted effects on uric acid levels." (PMID 38274913, 2023). "Type 2 diabetes mellitus is a chronic metabolic disorder resulting from insulin action and secretion defects." (PMID 38155289, 2023). "Accounting for over 90% of all global diabetes cases, type 2 diabetes mellitus (T2DM) is largely caused by the body cells' inability to fully respond to insulin, known as insulin resistance." (PMID 38116563, 2023).